FLCN (folliculin)
Diseases named in the same sentence as FLCN in open-access papers (continued):
Sharing a sentence is not in itself a finding about the gene and the disease.
rhabdomyoma (3 papers, 2014 to 2022). A benign mesenchymal tumor arising from skeletal or cardiac muscle. "Since the first description of BHD, additional clinical signs have been added to the syndrome and a large variety of benign tumors, such as rhabdomyomas (RM), have been linked with the FLCN gene mutation." (PMID 36338635, 2022). "Since then, an adult rhabdomyoma in a presumed parathyroid adenoma and a cardiac rhabdomyoma in an infant carrying a FLCN mutation have been described." (PMID 29744825, 2019). "The finding of an adult rhabdomyoma within the piriform fossa also raises questions as to the role of folliculin in the hypopharynx." (PMID 29744825, 2019). "Unfortunately, these studies could not be performed on our specimen because FLCN gene germline mutation would be present in all cells including the rhabdomyoma tumor cells." (PMID 25610687, 2014).
benign oncocytoma (2 papers, 2014 to 2021). "An example is the description of a patient with Cowden syndrome previously presenting a PTEN germline mutation, who harbored an oncocytic tumor presenting a somatic alteration in the Folliculin (FLCN) gene." (PMID 34177813, 2021). "The benign oncocytoma showed no chromosomal aberrations, whereas the high-grade oncocytic carcinoma showed loss of the 17p region housing FLCN (folliculin [Birt–Hogg–Dubé protein]), loss of 8p, and gain of 8q." (PMID 25275525, 2014).
diabetic retinopathy (2 papers, 2020 to 2024). "Of mechanistic importance the transcriptional landscape was consistent with upregulation of folliculin, a recently identified susceptibility gene for diabetic retinopathy." (PMID 38850100, 2024). "Independent cohorts of individuals with diabetes revealed an association of FLCN eQTLs with diabetic retinopathy." (PMID 33164750, 2020). "By integrating the gene expression findings with GWAS data, we implicated FLCN as a putative disease gene in diabetic retinopathy." (PMID 33164750, 2020). "We did not observe any evidence of horizontal pleiotropy (in which FLCN eSNPs are independently associated with both FLCN expression and diabetic retinopathy) confounding the analysis [HEIDI p>0.05 (p=0.2)]." (PMID 33164750, 2020). "Integrating genetic association with gene expression implicated FLCN as a disease gene for diabetic retinopathy." (PMID 33164750, 2020). "We detected an enrichment of the eQTLs from the glucose response genes among small association p-values and identified folliculin (FLCN) as a susceptibility gene for diabetic retinopathy." (PMID 33164750, 2020). "We demonstrated that independent FLCN eQTLs found both in the retina and GTEx tissues showed an enriched association with diabetic retinopathy, a finding that was replicated in a large independent cohort from the UKBB." (PMID 33164750, 2020). "We assessed the aggregated association of FLCN eSNPs (n = 272 eSNPs significant in the retina and 20 or more GTEx tissues) with diabetic retinopathy in the meta-GWAS and observed an enrichment for association with diabetic retinopathy (π1 = 0.9)." (PMID 33164750, 2020). "We show that altering the levels of FLCN expression impacts risk of diabetic retinopathy." (PMID 33164750, 2020). "Specifically, our studies implicated FLCN as a putative diabetic retinopathy susceptibility gene." (PMID 33164750, 2020). "(b) Bar plot comparing the true positive rate (π1), TPR, for association of diabetic retinopathy with all SNPs, all eSNPs, eSNPs from the 103 differential response genes to glucose (n = 7253), and eSNPs found in retina and >20 GTEx tissues for folliculin (FLCN) (n = 272)." (PMID 33164750, 2020). "Mendelian randomization provided evidence that genetic variation affects diabetic retinopathy through alterations in FLCN expression thereby suggesting that FLCN expression is a mediator of diabetic retinopathy." (PMID 33164750, 2020). "We show that one of these genes, folliculin (FLCN), is causally implicated in diabetic retinopathy based on results from genetic association testing and Mendelian randomization." (PMID 33164750, 2020). "We detected an aggregated effect of 14 independent FLCN eQTLs (r2 < 0.2) on the development of diabetic retinopathy through FLCN expression using multi-SNP Mendelian randomization (p=0.04)." (PMID 33164750, 2020). "Together, these findings support the presence of genetic variation at the FLCN locus affecting both FLCN expression and the development of diabetic retinopathy through the expression of FLCN." (PMID 33164750, 2020). "Expression of FLCN in response to glucose was greater in individuals with diabetic retinopathy." (PMID 33164750, 2020). "We then validated the FLCN association with diabetic retinopathy in a third cohort, the UK Biobank (UKBB), and found that the FLCN eSNPs were enriched for association with diabetic retinopathy in the UKBB (π1 = 0.73)." (PMID 33164750, 2020). "We applied Mendelian randomization to assess whether the level of FLCN expression affects the development of diabetic retinopathy." (PMID 33164750, 2020). "We first imputed retinal FLCN expression in the UKBB, and then estimated the effects of the estimated FLCN expression on diabetic retinopathy using summary data-based Mendelian randomization analysis (SMR)." (PMID 33164750, 2020).
diabetic retinopathy (continued). "In the LCLs derived from individuals with diabetes, FLCN was upregulated in response to glucose to a greater extent in individuals with diabetic retinopathy than in individuals with diabetes without retinopathy (log2FC difference = 0.27, p=2.5×10−3)." (PMID 33164750, 2020).
emphysema (2 papers, 2008 to 2012). "While these cystic changes are radiographically distinct from common forms of emphysema, increasing severity of folliculin-associated cystic changes are correlated with cigarette smoking." (PMID 19116017, 2008). "Because the majority of patients with folliculin mutations have radiographic evidence of pulmonary cysts, folliculin has been hypothesized to contribute to the development of emphysema." (PMID 19116017, 2008). "It has been hypothesized that folliculin may contribute to the development of emphysema and COPD in the general population." (PMID 19116017, 2008). "In addition, emphysema has been reported in lung resection specimens from non-smokers with folliculin mutations and FSP." (PMID 19116017, 2008). "We sought to address this question by characterizing the spectrum of folliculin sequence variation in a cohort of patients with severe early-onset COPD and in a case-control study of cases with severe emphysema and control smokers with normal spirometry." (PMID 19116017, 2008).
follicular lymphoma (2 papers, 2024 to 2025). Follicular lymphoma is a form of non-Hodgkin lymphoma characterized by a proliferation of B cells whose nodular structure of follicular architecture is preserved. "Studies have shown that RRAGC-activating mutations are found in approximately 10% of follicular lymphomas, with the mutated RRAGC protein showing increased binding to RPTOR (raptor) and significantly reduced interaction with the product of the tumor suppressor gene FLCN (follicle protein)." (PMID 40414942, 2025).
hereditary cancer (2 papers, 2022). Malignant neoplasms occurring in families at a rate greater than that expected by chance and caused by germline mutations in a specific gene.
liver fibrosis (2 papers, 2021 to 2025). "While previous studies showed that Flcn liver-specific conditional knockout (FlcnLiKO) mice are protected from developing liver fibrosis and damage upon high-fat diet exposure, the potential role of FLCN loss in liver carcinogenesis remained unexplored." (PMID 40189703, 2025). "Hence, the activity of FLCN could be a promising target for small molecule drugs to treat liver fibrosis by specifically activating autophagy." (PMID 34711912, 2021). "Still, little is known about how FLCN regulates a highly metabolic tissue such as the liver and, more specifically, the potential role of FLCN in liver fibrosis progression has never been investigated." (PMID 34711912, 2021).
lung adenocarcinoma (2 papers, 2020 to 2022). A carcinoma that arises from the lung and is characterized by the presence of malignant glandular epithelial cells. "Notably, lung adenocarcinoma has been reported in heterozygous FLCN knockout mice." (PMID 35125098, 2022).
osteosarcoma (2 papers, 2013 to 2024). A usually aggressive malignant bone-forming mesenchymal neoplasm, predominantly affecting adolescents and young adults. "To further investigate changes in endogenous FLCN expression during the late G2 phase, we arrested U2OS osteosarcoma cells at the G2/M boundary with nocodazole." (PMID 23874397, 2013).
renal oncocytoma (2 papers, 2010 to 2020). "FLCN was identified as the gene responsible for Birt-Hogg-Dubé (BHD) syndrome, a hereditary syndrome associated with the appearance of familiar renal oncocytomas." (PMID 32195250, 2020). "We further examined FLCN expression in BHDS-derived tumors as well as renal oncocytoma and chromophobe RCC." (PMID 21162720, 2010). "While germline mutations in FLCN cause BHDS, these mutations are not strongly associated with either sporadic chromophobe RCC or renal oncocytoma." (PMID 21162720, 2010).
uveal melanoma (2 papers, 2021 to 2026). A melanoma derived from melanocytes of the uveal tract. "Two patients with hybrid oncocytic tumors had biallelic inactivation of FLCN in a setting of Birt-Hogg-Dubé (BHD) syndrome associated with uveal melanoma and mesothelioma." (PMID 34767027, 2021). "In a recent Finnish study of 270 patients with uveal melanoma none had pathogenic FLCN variants." (PMID 41193855, 2026).
alcoholic steatohepatitis (1 paper, 2025). "Recent studies have shown that depletion of FLCN specifically in the mouse liver protects mice from developing fibrosis and inflammation upon exposure to a non-alcoholic steatohepatitis (NASH)-inducing diet." (PMID 40189703, 2025).
anaplastic thyroid carcinoma (1 paper, 2025). "Given that 24 of the 25 patients with FLCN driver alterations in the public datasets included in this study had anaplastic thyroid carcinoma, a subgroup analysis was conducted to evaluate the impact of FLCN on overall survival in this aggressive subset." (PMID 40277780, 2025).
asthma (1 paper, 2022). "Significant DMPs fall within genes involved in the TFG-β related pathways (e.g. BMP2, FLCN, ING2, PMEPA1, PRDM16, TGFB1I1 and TGFBR3), in line with previous studies that reported an association between these genes and the increased asthma risk." (PMID 35619695, 2022).
bowel cancer (1 paper, 2021). "While the germline alterations in certain susceptibility genes were also detected in the bowel cancer samples including FANCD2, CDH1, FLCN, MEN1, SDHB, and SLX4, which have been rarely reported in the Chinese population." (PMID 35154239, 2021).
breast fibroadenoma (1 paper, 2022). "One patient with c.1285delC mutation also presented breast fibroadenoma, which has been reported in another BHDS study with patients negative for pathogenic FLCN mutations." (PMID 35477461, 2022).
breast tumor (1 paper, 2022). "Thus, FLCN loss appears to induce TFE3-dependent breast tumor growth through activation of multiple mechanisms that reveal a general role of a deregulated FLCN/AMPK/TFE3 pathway in human cancers." (PMID 35070081, 2022).
cardiac hypertrophy (1 paper, 2025). "Other genes such as BSG (CD147) and HLA-A/C are involved in immune and matrix remodeling, while FLCN has been shown to regulate cardiac hypertrophy via mTORC1 signaling in murine models." (PMID 40832351, 2025).
cerebral cavernous malformations (1 paper, 2017). A disorder characterized by malformations in the structure of the capillaries in the brain. "Here we present a case of BHD syndrome and hereditary cerebral cavernous malformations due to the combination of pathogenic variants in both FLCN and CCM2 in the same individual." (PMID 27722904, 2017). "Genetic investigations revealed constitutional mutations in FLCN, associated with Birt–Hogg–Dubé syndrome (BHD) and CCM2, associated with familial cerebral cavernous malformation." (PMID 27722904, 2017).
cholangiocarcinoma (1 paper, 2025). A carcinoma that arises from the intrahepatic biliary tree (intrahepatic cholangiocarcinoma) or from the junction, or adjacent to the junction, of the right and left hepatic ducts (hilar cholangiocarcinoma). "Here, we demonstrate that hepatic loss of FLCN in mice results in cancer associated with inflammation and fibrosis with features of cholangiocarcinoma (CCA)." (PMID 40189703, 2025).
ciliopathy (1 paper, 2016). A genetic disorder of the cellular cilia or the cilia anchoring structures, the basal bodies, or of ciliary function. "In humans BHD has recently been described as a novel ciliopathy with FLCN being shown to localise to motile and non-motile cilia, centrosomes and the mitotic spindle." (PMID 27391801, 2016).
dementia (1 paper, 2023). Loss of intellectual abilities interfering with an individual's social and occupational functions. "Conversely, our patient presented with dementia, a clinical feature that, to date, has never been reported in patients carrying a pathogenic FLCN variant." (PMID 38249578, 2023). "Moreover, most FLCN mutations isolated from BHD patients are loss of function leading to decreased protein stability or inability to interact with FNIP1/2, likewise the C9orf72 repeat expansion found in ALS and dementia cases results in a loss of function due to reduced C9orf72 protein expression." (PMID 38249578, 2023). "We report a 74-years-old woman diagnosed with dementia and carrying a FLCN alteration in absence of any sign of BHD." (PMID 38249578, 2023).
endometrial adenocarcinoma (1 paper, 2020). "Furthermore, similar results were obtained in Hec-1-B endometrial adenocarcinoma cells upon knockdown of FLCN, excluding a cell-type-specific effect." (PMID 33014885, 2020).
endothelial dysfunction (1 paper, 2021). In vascular diseases, endothelial dysfunction is a systemic pathological state of the endothelium (the inner lining of blood vessels) and can be broadly defined as an imbalance between vasodilating and vasoconstricting substances produced by (or acting on) the endothelium. "The relationship between AR, FLCN, and endothelial dysfunction requires further study." (PMID 34447638, 2021).
Familial adenomatous polyposis (1 paper, 2016). Familial adenomatous polyposis (FAP) is characterized by the development of hundreds to thousands of adenomas in the rectum and colon during the second decade of life. "We previously reported that the de novo FLCN mutation occurred in descendents of patients with familial adenomatous polyposis, a disease caused by germline mutation of the APC gene." (PMID 27871249, 2016).
follicular thyroid carcinoma (1 paper, 2014). "To determine whether loss of FLCN in human cancer cells also conferred an advantage in energy homeostasis, we used the follicular thyroid carcinoma cells FTC-133 lacking FLCN expression, which we rescued for FLCN using stable transfection." (PMID 24763318, 2014).
gonococcal infection (1 paper, 2020). "To analyze the function of FLCN in gonococcal infection, we generated a stable shRNA-expressing HeLa2000 cell line where FLCN expression was downregulated." (PMID 33014885, 2020). "We, therefore, investigated the role of FLCN in cellular polarization and in particular the fate of the adherence junction protein E-cadherin in gonococcal infection." (PMID 33014885, 2020). "Additionally, FLCN inhibits autophagy upon gonococcal infection." (PMID 33014885, 2020).
hamartoma (1 paper, 2019). A benign and excessive tumor-like growth of mature cells and normal tissues which grow in a disorganized pattern. "It is possible that the presence of FLCN mutations in patients with hamartomas is more common than is widely known but the limited awareness of BHD is resulting in cases going unrecognised." (PMID 29744825, 2019).
lipomatosis (1 paper, 2023). A neoplastic process characterized by diffuse overgrowth of mature adipose tissue. "The lipomatosis could be either a direct effect of the PRDM10 variant, for example by gene expression changes other than FLCN reduction, or it may be an adipose tissue-specific effect of folliculin repression and downstream TFE3/TFEB activation, which is described to play a role in adipose tissue." (PMID 36440963, 2023). "In our cohort of more than 300 BHD and BHD-like patients, we have no other families with such extensive lipomatosis and no families with definite BHD without an identifiable FLCN pathogenic variant." (PMID 36440963, 2023).
liver cancer (1 paper, 2025). An epithelial or non-epithelial malignant neoplasm that arises from the liver. "To further assess the role of FLCN in hepatocarcinogenesis, we induced liver injury and recovery by administering a 25 mg/kg dose of diethylnitrosamine (DEN) in FlcnLiKO and control mice at post-natal stage (P) 21, a well-established protocol for liver cancer induction." (PMID 40189703, 2025). "Notably, depletion of TFE3, but not TFEB, in the liver of FlcnLiKO mice fully rescues the cancer phenotype and normalized mTORC1 signaling, highlighting TFE3 as the primary driver of liver cancer and mTORC1 hyperactivity in the absence of FLCN." (PMID 40189703, 2025).
liver cyst (1 paper, 2025). "A correlation between FLCN mutations and liver cyst development has been reported but remains controversial." (PMID 40189703, 2025).
liver disease (1 paper, 2021). "FLCN seemed to be involved in regulating autophagy in a severe liver disease setting and it is possibly the primary mechanism of action by which loss of Flcn reduces liver fibrosis." (PMID 34711912, 2021).
oncocytic thyroid carcinomas (1 paper, 2025). "While both conventional oncocytic thyroid carcinomas and FLCN-mutant tumors feature mitochondrial accumulation, they differ markedly in their molecular drivers, mitochondrial function, and genomic context." (PMID 40277780, 2025).
osteoporosis (1 paper, 2020). A condition of reduced bone mass, with decreased cortical thickness and a decrease in the number and size of the trabeculae of cancellous bone (but normal chemical composition), resulting in increased fracture incidence. "A number of the genes highlighted in this study present strongly as having a potential role in bone biology, including CPE, FBN2, FLCN and RIPK3, and our results support the growing body of evidence suggesting that the CPE gene may exert pleiotropic effects on type 2 diabetes and osteoporosis." (PMID 32216834, 2020).
poorly differentiated thyroid carcinoma (1 paper, 2025). "We also presented a patient with an oncocytic, poorly differentiated thyroid carcinoma with an oncogenic biallelic somatic FLCN mutation." (PMID 40277780, 2025).
renal angiomyolipoma (1 paper, 2024). "We also identified 5 patients with unexpected renal angiomyolipoma and 6 novel FLCN mutations." (PMID 39300538, 2024).
thyroid (1 paper, 2025). "Including FLCN in genetic testing could improve tumor detection and characterization, particularly in BHD patients who may benefit from routine thyroid screening." (PMID 40277780, 2025).